IGKV1-39 (immunoglobulin kappa variable 1-39)
Description:
V region of the variable domain of immunoglobulin light chains that participates in the antigen recognition. Immunoglobulins, also known as antibodies, are membrane-bound or secreted glycoproteins produced by B lymphocytes. In the recognition phase of humoral immunity, the membrane-bound immunoglobulins serve as receptors which, upon binding of a specific antigen, trigger the clonal expansion and differentiation of B lymphocytes into immunoglobulins-secreting plasma cells. Secreted immunoglobulins mediate the effector phase of humoral immunity, which results in the elimination of bound antigens. The antigen binding site is formed by the variable domain of one heavy chain, together with that of its associated light chain. Thus, each immunoglobulin has two antigen binding sites with remarkable affinity for a particular antigen. The variable domains are assembled by a process called V-(D)-J rearrangement and can then be subjected to somatic hypermutations which, after exposure to antigen and selection, allow affinity maturation for a particular antigen.
Synonyms: IGKV139; O12; O12a
Tractability: Antibody: its Gene Ontology location is reachable by antibodies, with high confidence; UniProt places it where antibodies can reach, with medium confidence; UniProt predicts a signal peptide or a membrane-spanning region.
Gene: Immunoglobulin variable (V) gene on chromosome 2 (89,319,625 to 89,320,146, reverse strand). Ensembl gene ENSG00000242371.
Subcellular location: Secreted; Cell membrane
Pathways (Reactome):
Immune System: Antigen activates B Cell Receptor (BCR) leading to generation of second messengers; CD22 mediated BCR regulation; Classical antibody-mediated complement activation; FCERI mediated Ca+2 mobilization; FCERI mediated MAPK activation; FCERI mediated NF-kB activation; FCGR activation; Fc epsilon receptor (FCERI) signaling; Immunoregulatory interactions between a Lymphoid and a non-Lymphoid cell; Initial triggering of complement; Regulation of Complement cascade; Regulation of actin dynamics for phagocytic cup formation; Role of LAT2/NTAL/LAB on calcium mobilization; Role of phospholipids in phagocytosis
Disease: FCGR3A-mediated IL10 synthesis; FCGR3A-mediated phagocytosis; Potential therapeutics for SARS
Hemostasis: Cell surface interactions at the vascular wall
Vesicle-mediated transport: Scavenging of heme from plasma
Gene Ontology:
Molecular function: antigen binding
Biological process: immune response
Cellular component: blood microparticle; extracellular exosome; extracellular region; immunoglobulin complex; plasma membrane
Homologues: Orthologues: mouse Igkv15-103 (74% identical). Paralogues in human: IGKV1D-39 (100% identical), IGKV1-12 (91% identical), IGKV1-9 (91% identical), IGKV1-6 (91% identical), IGKV1D-12 (91% identical), IGKV1D-13 (91% identical), IGKV1D-16 (90% identical), IGKV1OR2-108 (90% identical), IGKV1-16 (89% identical), IGKV1-17 (89% identical), IGKV1-27 (89% identical), IGKV1-5 (89% identical), and 81 more.
Diseases named in the same sentence as IGKV1-39 in open-access papers:
IGKV1-39 is named in the same sentence as 1 disease in open-access papers, as found by Europe PMC text mining. Sharing a sentence is not in itself a finding about the gene and the disease. The quoted sentences say what the papers report.
kidney diseases (1 paper, 2019). "Our present study strongly implicated the IGKV1-39 gene in crystalline light chain inclusion-associated kidney diseases." (PMID 30702553, 2019).